IL4 (interleukin 4)
Diseases named in the same sentence as IL4 in open-access papers (continued):
Sharing a sentence is not in itself a finding about the gene and the disease.
gastritis (9 papers, 2008 to 2025). Inflammation of the stomach. "H. pylori eradication has been shown to increase IL4 levels and IL4 treatment decreases pathogen density and the severity of gastritis in H. felis-infected mice." (PMID 40667878, 2025). "In the positive control group infected with H. pylori pathogenic strain, isolated from patients with gastritis, there was a huge increment in IFN-γ, while the rate of IL-4 decreased." (PMID 35083009, 2021). "A statistically significant majority of gastritis (62.1%, P=0.0008) patients were either heterozyote (CT) or homozygote (TT) for IL-4 C-590T SNP, as compared to only 28.3% of H. pylori-positive asymptomatic controls." (PMID 27677314, 2017). "In terms of susceptibility to gastritis, seropositivity to HP-NAP projected a risk impact of 4.62 fold (OR=4.62, 95% CI=1.50-14.22), which when present in IL-4 -590 T carriers augmented the risk up to 9.7 fold (OR=9.70, 95% CI=2.06-45.69)." (PMID 27677314, 2017). "Through modulation of the Th1/Th2 balance, IL-4 is a regulator of the TME in gastritis." (PMID 41376630, 2025). "In addition, IL-4 significantly increased in patients with moderate gastritis compared with Hp- individuals (P=0.008)." (PMID 39807418, 2024). "Similarly, IL-4 showed a significant increase in patients with moderate gastritis compared with the Hp- subjects." (PMID 39807418, 2024). "Interestingly, H. pylori infection in Il4−/− mice on a C57BL/6 background resulted in more severe gastritis and higher levels of IFN-γ production by stimulated splenocytes." (PMID 27895717, 2016). "Therefore, IL-4 and IL-10 function as protective factors in gastritis." (PMID 40264171, 2025). "The amounts of IL-2, IL-4, IL-17A, IL-17F, IL-22, TNF-α, and TFN-γ were significantly different in patients with gastritis compared with Hp- subjects." (PMID 39807418, 2024). "Infected Il-4 (-/-) mice had increased IFN-γ level and more severe gastritis." (PMID 40264171, 2025). "Consistent with this suggestion, Ifng−/− mice on a C57BL/6 background did not develop gastritis to H. pylori infection, while the splenocytes from these animals produced significantly more IL-4 in response to stimulation than those from wild type animals." (PMID 27895717, 2016). "Furthermore, gastric CD4+ T cells recovered from BALB/cnu/nu mice produced significant quantities of IL-17 or IFN-γ but not IL-4, suggesting that Th1 and/or Th17 cells function as terminal effectors of gastritis development in AID−/− mice." (PMID 18716662, 2008).
Giardia infection (9 papers, 2017 to 2025). "For instance, variations in the immune response genes, such as those regulating the production of interleukins (IL-4, IL-10), may predispose individuals to persistent giardiasis." (PMID 40400829, 2025). "While several researchers observed a high level of IL-2, IL-4, and IL-10 in the infected group as compared to the control group, there are reports that state the level of IL-4 was decreased in patients with giardiasis." (PMID 36065350, 2022). "Proinflammatory chemokines, including TNF-α, and B lymphocyte activating interleukins, such as IL-4 and IL-5 belong to the chemokine profile described in Giardia infection." (PMID 34778111, 2021). "First we studied cytokines that earlier have been shown to be up-regulated during Giardia infections in mice, i.e. IL-1, IL-2, IL-4, IL-5, IL-9, IL-10, IL-12, IL-17a, IL-17c, IFN-γ, TGF-β, and TNF-α." (PMID 34335577, 2021). "TNF-α-deficient mice do not appear to be related to mechanisms previously shown to control Giardia infections, including IgA production, mast cell responses, IL-6 or IL-4 expression." (PMID 28979269, 2017). "Rather, prior Giardia infection resulted ingreater IL-4 and IL-13 and increased IL-9, a potential marker of mast cell activity." (PMID 28750066, 2017). "Although the Th1 cytokine IFN-γ and the Th2 cytokines IL-4 and IL-5 have been shown to be elevated in Giardia-infection models, both IFN-γ-deficient and IL-4-deficient mice can still eliminate Giardia, suggesting that the Th1 and Th2 responses are not essential for clearance." (PMID 32283818, 2020).
Glucose intolerance (9 papers, 2011 to 2025). Glucose intolerance (GI) can be defined as dysglycemia that comprises both prediabetes and diabetes. "Eosinophil-derived IL-4 and IL-13 promote M2 macrophage polarization and adipocyte maturation, enhancing lipid storage and insulin sensitivity, whereas eosinophil deficiency leads to impaired adipogenesis, ectopic lipid deposition, and glucose intolerance." (PMID 41010970, 2025). "IL-4 was used to treat diet-induced obese mice and protected them from weight gain and glucose intolerance by activating the STAT6 pathway." (PMID 31297120, 2019). "Adipocytes represent another important source of IL-4 and IL-13; these are also well known for their ability to induce M2 macrophages, which are protective against glucose intolerance." (PMID 29387059, 2017). "IL-4 and IL-13 are also well known for their ability to induce M2 macrophages, which are protective against glucose intolerance." (PMID 26146464, 2015). "While the IL-4/STAT6 pathway has been consistently shown to be protective against glucose intolerance, the role of Th2 cells in this disease has been much less well defined." (PMID 26146464, 2015). "IL-4 and IL-13, which are both induced by type 2 immune responses, decrease inflammation in metabolic organs by inducing M2 polarization of macrophages, leading to the improvement of systemic glucose intolerance in mice." (PMID 34073755, 2021). "Administration of IL-4 to mice with diet-induced obesity (DIO) protects them from weight gain and glucose intolerance, and this involves activation of the STAT6 pathway." (PMID 29387059, 2017). "Administration of IL-4 to DIO mice protects them from weight gain and glucose intolerance in a pathway that involves STAT6 activation and PPARα suppression." (PMID 26146464, 2015).
Hashimoto thyroiditis (9 papers, 2011 to 2024). An autoimmune disorder caused by the production of autoantibodies against thyroid tissue. "Cytometric Bead Array (CBA) analysis of pro and anti-inflammatory cytokines (IFN-gamma, IL-2, IL-6, IL-17 A, TNF-alpha and IL-4, IL-10) was done in 15 PTC irrespective of Lymphocytic Thyroiditis (LT) and 16 Hashimoto’s Thyroiditis (HT) cases." (PMID 37563607, 2023).
heart failure (9 papers, 2012 to 2025). Inability of the heart to pump blood at an adequate rate to meet tissue metabolic requirements. "Urine IL-4 is associated with myocardial fibrosis and remodeling in heart failure by the concentration of urine IL-4 in patients with HF and its relationship to markers of myocardial fibrosis and left ventricular volume." (PMID 37047468, 2023). "The concentrations of IL-5, IL-6 and IL-9 were significantly higher in the saliva of heart failure patients with both NS and HS compared to the control group, while IL-4 level was significantly higher only in heart failure patients with HS." (PMID 36300113, 2022). "Elevated plasma levels of IL-4 have been reported in patients with CAD, heart failure, heart fibrosis and cardiomyopathies." (PMID 39091640, 2024).
hepatitis B (9 papers, 2014 to 2023). "There are a few exceptions: for example meta-analyses for hepatitis B vaccine responses found evidence that variants in class II HLA and interleukin-4 (IL-4) were significantly associated with antibody responses." (PMID 25699041, 2015). "An earlier investigation revealed that lower serum IL-4 concentrations accompany the acute and convalescent phases of hepatitis B virus infection." (PMID 37598258, 2023). "The results of the IFN-γ/IL-4 ratio of fucoidan-based vaccines were considerable and will improve the efficacy of hepatitis B vaccines." (PMID 32168741, 2020). "IL-4 also plays a crucial role in hepatitis B vaccination-induced brain development and cognition." (PMID 31901235, 2020). "Not coincidentally, in an analysis of the immune response to hepatitis B virus infection, it was found that patients who recovered from acute hepatitis B virus infection activated the Th2 release of IL-4 and IL-10, which induced the B-cell production of antibodies." (PMID 26824828, 2016). "The impact of IL-4 gene polymorphisms in the pathogenesis of HBV infection has been investigated, and numerous studies have suggested that IL-4 variants play pivotal roles in hepatitis B vaccine response and HBV infection risk." (PMID 25295591, 2014).
keratoconus (9 papers, 2011 to 2025). A degenerative, structural disorder of the eye, characterized by a cone-shaped protrusion of the cornea. "The presence of elevated IL-4 levels in stable keratoconus patients align with this immunological context." (PMID 40980981, 2025). "Important differences were found in IL-4 levels between keratoconus patients and relatives and between relatives and controls (mean difference of 302.42, p < 0.0016 and 219.16, p < 0.033, Tukey's HSD procedure)." (PMID 30245588, 2018). "The multiplex data implicate reductions in TH1 (IL-12, TNF-α, IFN-γ), and possibly TH2 cytokines (IL-4 and IL-13) in keratoconus." (PMID 21298010, 2011). "Both IL-4 and IL-13 cytokines were also reduced in keratoconus, and the decrease in IL-4, as measured by conventional ELISA, was statistically significant." (PMID 21298010, 2011). "Based on the reported link between atopy and keratoconus, it is conceivable that IL-4 levels would be higher in the keratoconus group." (PMID 21298010, 2011). "Thus, separate from atopy, the decrease in IL-4 we see may be pertinent to the pathophysiology of keratoconus itself." (PMID 21298010, 2011). "Our aim was to determine the concentration of IL-4, IL-6, IL-10, RANTES, IFN gamma, and TNF alpha in the tear film of patients with keratoconus and their first degree family members." (PMID 30245588, 2018). "The means of IFN gamma, IL-10, IL-1 beta, IL-4, IL-6, and TNF alpha had a significant difference between the keratoconus patients and the normal subjects." (PMID 30245588, 2018). "Partly in line with these results, increased tear levels of MMP-1, MMP-3, MMP-7, MMP-9, and MMP-13; IL-4, IL-5, IL-6, and IL-8, and TNF-α, -β were found in keratoconus." (PMID 26881061, 2016). "IL-1 beta and IL-4 presented the most notable significant differences between the keratoconus and control groups as well as between the relatives and normal subjects." (PMID 30245588, 2018). "Interleukin (IL)-1β, IL-4, IL-6, IL-10, IL-12, IL-13, IL-17, interferon (IFN)-γ, chemokine C-C motif ligand 5 (CCL5) and tumor necrosis factor (TNF)-α were tested in tear samples and sera of keratoconus and control individuals by multiplex immuno-bead assays." (PMID 21298010, 2011). "Elevated levels of interleukin- (IL-) 1b, IL-4, IL-5, IL-6, IL-8, and IL-17; tumor necrosis factor (TNF)-α, -β; interferon- (IFN-) γ; matrix metalloproteinase- (MMP-) 1, MMP-3, MMP-7, MMP-9, and MMP-13; Cathepsin B; and Lipocalin-1 have been found in the tears of patients with keratoconus." (PMID 26881061, 2016). "Decreased IL-4 in keratoconus may have broad immune and non-immune consequences that should be considered in the context of corneal thinning and abnormal stromal extracellular matrix (ECM)." (PMID 21298010, 2011). "Thus, decreases in IL-4 and IL-13 suggest that TH2 responses may be dampened in keratoconus." (PMID 21298010, 2011).
liver cancer (9 papers, 2017 to 2025). An epithelial or non-epithelial malignant neoplasm that arises from the liver. "In liver cancer, specific cytokines such as Interleukin-12 (IL-12), Interleukin-10 (IL-10), and Interleukin-4 (IL-4) have been studied for their distinctive roles in modulating the tumour microenvironment." (PMID 40544399, 2025). "Therefore, elevated levels of these inflammatory markers (i.e. IL-1β, IL-4, IL-6, IL-10, TNF-α and C-reactive protein) increase the risk of liver cancer development." (PMID 37990536, 2023). "THP‐1 cells were co‐cultured with liver cancer cell line H22, and M2 polarization was induced in THP‐1 by IL‐4/13 to simulate tumour‐induced macrophage polarization." (PMID 33742511, 2021). "Interestingly, compared with TPH1 + PMA + L02-SCR group, it is showed for the M2 polarization in TPH1 + PMA + L02-Sh group and TPH1 + PMA + IL-4 + IL-13 group, indicated decreased FPN1 promoted liver cancer cell M2 polarization." (PMID 34183746, 2021).
malnutrition (9 papers, 2014 to 2024). Inadequate nutrition resulting from poor diet, malabsorption, or abnormal nutrient distribution. "Second, Type 2 cytokines involved are known to induce susceptibility to TB infection and disease However, our data suggest that even in the presence of TB disease, IL-4 and IL-5 levels are low, possibly due to the predominant influence of malnutrition in suppressing Th2 responses." (PMID 37324745, 2023). "Malnutrition by a low-protein diet in these animals increased the growth defects and the effects were seen already after 13 days, similar to what we see in our SG model, and it reduced the expression of the cytokines IL-4 and IL-5 compared to Giardia infected well-nourished mice." (PMID 34335577, 2021). "Other cytokines were mostly found to be elevated in malnutrition: IL10 was elevated in four of five studies, so was IL-4 and soluble receptors to Tumour Necrosis Factor-α." (PMID 25153531, 2014). "Malnutrition promotes the phenotypic transformation of immune cells to pro-inflammatory phenotypes, secreting pro-inflammatory cytokines such as IL-1β, IL-6, IL-8, TNF-α, and IL-2, while anti-inflammatory cytokines such as IL-1 receptor antagonists, IL-4, IL-10, and IL-13 decrease." (PMID 35003070, 2021).
peanut allergy (9 papers, 2015 to 2025). "A blockade of IL-4/IL-13 signaling can suppress IgE production and Th2 cytokine responses in a mouse model of peanut allergy." (PMID 40005151, 2025). "In both humans and mice, the type 2 cytokines, IL-4 and IL-13, play critical roles in the development of IgE-mediated intestinal peanut allergy." (PMID 32497050, 2020). "The type 2 cytokines, IL-4 and IL-13, play critical roles in IgE-mediated intestinal peanut allergy in humans and mice." (PMID 32497050, 2020). "In vitro, allergen-stimulated T cells and T-cell clones generated from patients with peanut allergy produced increased levels of the type 2 cytokines IL-4, IL-5, and IL-13." (PMID 32497050, 2020). "The ethanol extract of D. superbus has been shown to suppress the production of IgE in a human B cell line, a murine model of peanut allergy, interleukin-4 (IL-4), IL-13 and eotaxin." (PMID 26513163, 2015). "Peanut allergy in humans is Th2-dependent, during sensitization to peanut, priming of allergen-specific Th2 cells results in the production of Th2 cytokines (such as IL-4 and IL-13), which are responsible for class switching by B cells, allowing IgE production." (PMID 30988664, 2019). "Maternal peanut allergy induced epigenetic alteration of the IL4 promoter in their offspring, which correlated with a Th2 biased responses (IL-4 and IgE production)." (PMID 34959895, 2021). "We demonstrated that the critical source of IL-4 in this peanut allergy model was the naïve CD4 T cell, which effected autocrine/paracrine IL-4 signalling to amplify and stabilize the Th2 state." (PMID 29757238, 2018).
Peri-Implantitis (9 papers, 2018 to 2025). An inflammatory process with loss of supporting bone in the tissues surrounding functioning DENTAL IMPLANTS. "Within the limitations of this study, it was possible to conclude that the geneexpression of IL-4 was increased in peri-implant tissues retrieved from sitesaffected by peri-implantitis when compared with healthy tissues." (PMID 37466520, 2023). "Within the limitations of thisstudy, the results showed that in tissues affected by peri-implantitis, onlylevels of Il-4 were increased when compared with tissues in the controlgroup." (PMID 37466520, 2023). "Other cytokines found in peri-implantitis include IL-4, IL-6,IL-8, IL-10, IL-12, and IL-17." (PMID 39195095, 2024). "The study revealed that, concerning inflammatory factors, IL-12 and TNF-α were higher in severe peri-implantitis, followed by initial peri-implantitis and mucositis, while IL-4 was higher in healthy projects, followed by mucositis, severe, and initial peri-implantitis." (PMID 35846759, 2022). "During the treatment of peri-implant mucositis and peri-implantitis there were minimal effects of non-surgical treatment alone on the investigated inflammatory biomarkers (IL-4, IL-10, and IL-12, TNF-a, RANKL, OPG IL-1β, IL-6, TNF-α, MCP-1/CCL2, MIP-1α/CCL3, IFN-γ, MMP-8, sRANKL, OPG and G-CSF)." (PMID 36360962, 2022). "This study evaluated the presence of cytokines (IL-1β, IL-2, IL-4, IL-6, MCP-1, MIP-1α, MIP-1β, and TNF-α) and human herpesvirus (HSV1, HSV2, EBV, CMV, VZV, HHV6, HHV7, and HHV8) in saliva samples taken from subjects with and without peri-implantitis." (PMID 30158834, 2018).
peritonitis (9 papers, 2011 to 2023). Inflammation of the peritoneum (tissue that lines the abdominal wall and covers most of the organs in the abdomen). "The production of IL-4 and IL-13 appears to be important to resolve inflammation since deficiency of IL-4, the IL-4 receptor or natural killer cells increased peritonitis severity." (PMID 31413937, 2019). "Consistent with other studies demonstrating a protective and anti-inflammatory role for RELMα, we show that RELMα is only expressed in naïve small peritoneal macrophage but is expressed by small and large peritoneal macrophages in IL-4-induced peritonitis." (PMID 34349768, 2021). "We next determined in vivo impacts of IL-4 and IFNγ on the development of neutrophil-DC hybrids in thioglycollate-induced peritonitis lesions." (PMID 24278484, 2013). "Wsh mice reconstituted with IL-4-conditioned mast cells are more likely to survive peritonitis than Wsh mice reconstituted with unconditioned mast cells." (PMID 22110673, 2011). "Indeed, relative expression level of Arg1 to a control house keeper gene (GAPDH) in these peritoneal-elucidated cells at healing stage of peritonitis was as high as that in in vitro-activated M2MΦs by recombinant IL-4." (PMID 27731330, 2016). "Previous studies suggest that IL-4 and IL-13, two cytokines known to induce STAT6 activation, are not involved in STAT6 phosphorylation during zymosan-induced peritonitis." (PMID 35327639, 2022). "However, in the present study, we found that, similar to IL-4 and IL-13, the TSG6 mRNA and/or protein levels remained the same in PLF, peritoneal macrophages, and spleen after zymosan injection, indicating that TSG6 is not involved in the STAT6 pathway during zymosan-induced peritonitis." (PMID 35327639, 2022).
psychosis (9 papers, 2013 to 2026). "In order to assess the Th1/Th2 cytokines balance between subjects with first-episode psychosis and healthy controls, we calculated the IFNγ/IL-4 ratio." (PMID 22749891, 2013). "In contrast, there was a significant decrease in IFNα2 and IL-4 cytokine levels in ASD compared to both controls and psychotic disorders." (PMID 42239763, 2026). "In first-episode psychosis, interferon-γ (IFN-γ), IL-1RA, IL-1β, IL-6, IL-8, IL-10, IL-12, sIL-2R, TGF-β, and TNF were all significantly increased, and levels of IL-4 were significantly decreased." (PMID 32256401, 2020). "Other potential state markers are IL-4 and IL-10, although in this case, only in chronic schizophrenia and not in the first episodes of psychosis." (PMID 36830990, 2023). "In addition, decreased IL-4 levels were observed in the chronic EOP population compared to adult AChR and HC, which may indicate that reduced peripheral levels of IL-4 are typical only of AChR patients with early-onset psychosis and comorbid minor neurological disorders." (PMID 34501305, 2021).